PLK2 (polo like kinase 2)
Diseases named in the same sentence as PLK2 in open-access papers (continued):
Sharing a sentence is not in itself a finding about the gene and the disease.
glioblastoma (9 papers, 2019 to 2025). The most malignant astrocytic tumor (WHO grade IV). "This accounts for glioblastoma, hepatocellular carcinoma, acute myeloid leukemia, and for B-cell malignancies where PLK2 is epigenetically silenced, as well as for cervical cancer where PLK2 exhibits anti-proliferative and apoptosis-promoting effects." (PMID 34065956, 2021). "PLK2 served as a novel biomarker for the prognosis of human glioblastoma." (PMID 38520027, 2024). "In glioblastoma, PLK2 is negatively correlated with the central notch signaling pathway." (PMID 34065956, 2021). "Among which, CDC73, PSMC2, SOCS3, and ETV4 were substantially upregulated; whereas PLK2 and LMO7 were substantially downregulated in glioblastoma cells than that in control." (PMID 41318472, 2025). "Polo like kinase 2 (PLK2), a member of the serine/threonine kinases family, could induce glioblastoma resistance to temozolomide by regulating Hes family BHLH transcription factor 1 (HES1) and notch signaling." (PMID 37700319, 2023). "In glioblastoma multiforme (GBM), reduced PLK2 expression indicates treatment resistance and poor prognosis; overexpression of PLK2 could repress the tumor characteristics of GBM cell and lower the incidence of acquired TMZ resistance." (PMID 35898867, 2022).
acute myeloid leukemia (7 papers, 2011 to 2024). Acute myeloid leukemia (AML) is a group of neoplasms arising from precursor cells committed to the myeloid cell-line differentiation. "miR-126 was found to target a tumor suppressor PLK2 and further inhibit apoptosis and increase the viability of acute myeloid leukemia cells." (PMID 23285182, 2012). "Moreover, some studies revealed that microRNA-126 repressed apoptosis of acute myeloid leukemia cells and enhanced the colony-forming ability of mouse bone marrow progenitor cells through targeting Polo-like kinase 2 (PLK2)." (PMID 22900072, 2012). "More recent studies from our groups have shown methylation in the PLK2 CpG island in other haematological malignancies including multiple myeloma, acute myeloid leukemia (AML) and myelodysplastic syndromes (MDS)." (PMID 22289679, 2012). "As a low-molecular-weight, ATP-competitive kinase inhibitor, BI6727 effectively inhibits PLK1, PLK2, and PLK3 and has shown promising effects in various xenograft models and patients with acute myeloid leukemia (AML) (Gjertsen and Schöffski, 2015)." (PMID 39763588, 2024). "Moreover, it has been reported that miR-126 inhibits apoptosis of acute myeloid leukemia (AML) cells and enhanced the colony-forming ability of mouse bone marrow progenitor cells through targeting Polo-like kinase 2 (PLK2), a tumor suppressor." (PMID 21304604, 2011).
glioma (6 papers, 2015 to 2025). A benign or malignant brain and spinal cord tumor that arises from glial cells (astrocytes, oligodendrocytes, ependymal cells). "Taken together, these data demonstrated that knock-down of PLK2 is associated with pathological malignancy and revealed severe outcomes in glioma." (PMID 33176854, 2020). "Kaplan-Meier survival analysis showed that glioma patients with lower expression of PLK2 represented a shorter overall survival when compared with higher PLK2 expression." (PMID 33176854, 2020). "CDK7 inhibition has previously been reported to downregulate EGFR in high-grade glioma and PLK2 in a lung cancer cell line." (PMID 32155786, 2020). "A PLK2 inhibitor has been studied for the first time in a glioma cell in this work." (PMID 35256538, 2022). "This study is the first to use a PLK2 inhibitor in a glioma cell." (PMID 35256538, 2022). "Notably, PLK2 overexpression significantly elevated the apoptosis rate of resistant glioma cell lines under the treatment of TMZ." (PMID 33176854, 2020). "Moreover, the apoptotic rate of glioma cells transduced with PLK2 overexpression lentivirus increased significantly compared with its negative control." (PMID 33176854, 2020). "The results indicated that PLK2 was likely to be enriched in low grade gliomas compared with GBM." (PMID 33176854, 2020). "Furthermore, the glioma patients were divided into 2 groups according to the GIS of PLK2 expression." (PMID 33176854, 2020). "Furthermore, Rembrandt database was used to investigate the expression pattern of PLK2 in different pathological subtypes of glioma including astrocytoma, GBM and oligodendroglioma." (PMID 33176854, 2020). "Aneuploid PA differentially expressed genes involved in CNS development, the unfolded protein response, and regulators of genomic stability and the cell cycle (MDM2, PLK2),whose correlated programs were overexpressed specifically in aneuploid PA compared to other glial tumors." (PMID 26378811, 2015). "In addition, PLK2 may contribute to the poor prognosis of glioma patients through other cascades." (PMID 35256538, 2022). "We utilized RNA-seq data from multiple databases, including Gene Expression Omnibus (GEO), the Cancer Genome Atlas (TCGA), and the Chinese Glioma Genome Atlas (CGGA), and conducted experiments on human glioma cell lines to explore PLK2's expression and function." (PMID 39927502, 2025). "It is obvious that non-tumor tissues exhibited the highest expression of PLK2 compared with other types of glioma." (PMID 33176854, 2020). "The results indicated that PLK2 was expressed predominantly in the cytoplasm cytomembrane of low-grade glioma and non-tumor samples, however, the staining was significantly lower in GBM samples." (PMID 33176854, 2020). "Notably, although the samples from our center indicated that there might be a correlation between PLK2 expression and clinical degree of glioma, data from other databases including TCGA, CGGA, Rembrandt indicated an ambiguous correlation between PLK2 and tumor grade or cancer pathological subtypes." (PMID 33176854, 2020).
myeloma (6 papers, 2012 to 2025). "Our findings demonstrated that KIRA8 treatment suppressed the transition to the G2/M phase in myeloma cells, followed by the PLK2-dominant inhibitor exhibiting a similar effect as KIRA8." (PMID 32878237, 2020). "Overall, these findings suggested that the mRNA and protein expressions of PLK2 were increased in human myeloma cells." (PMID 32878237, 2020). "Nevertheless, this is the first pilot study to demonstrate that the PLK2 expression was increased in the BM of patients with myeloma, whereas it was constant in those of control subjects." (PMID 32878237, 2020). "A PLK2-dominant inhibitor, TC-S7005, significantly reduced the cell viability and increased apoptosis in IM-9 myeloma cells." (PMID 32878237, 2020). "This study demonstrated that targeting PLK2 by miR-126 inhibits cell apoptosis and increases cell viability, indicating the silencing of PLK2 enhances the cell viability in acute myeloma cell lines." (PMID 33176854, 2020). "KIRA8 and PLK2 inhibition exerted anti-myeloma effects with apoptosis induction and the regulation of cell proliferation." (PMID 32878237, 2020). "Accordingly, we examined these biological characteristics of PLK2 in myeloma cells." (PMID 32878237, 2020). "In addition, this study identified PLK2 as a novel key target of IRE1α, demonstrating its inhibitor-induced anti-myeloma effects." (PMID 32878237, 2020). "Additionally, in acute myeloma cell lines, targeting PLK2 by miR-126 induces the down-regulation of PLK2 and inhibits cell apoptosis and increases cell viability." (PMID 33176854, 2020). "Finally, encouraged by the regulatory effect of IRE1α on PLK2, we assessed if the PLK2 expression was, indeed, increased in patients with myeloma." (PMID 32878237, 2020). "Myeloma patients overexpress UPR markers XBP1, BiP, ATF4, and CHOP, as well as polo-like kinase 2 (PLK2)." (PMID 40563622, 2025). "Together, PLK2 expression, but not PLK1, was regulated by IRE1α, and its pharmacological inhibition induced apoptosis, demonstrating the cell-cycle arrest in human myeloma cells." (PMID 32878237, 2020).
B cell lymphomas (5 papers, 2013 to 2023). "Loss of PLK2 expression by promoter CpG island methylation is one of the most common epigenetic events in B-cell lymphomas." (PMID 23516355, 2013). "Plk2 is frequently silenced in a methylation-dependent manner in several B cell lymphomas and primary lymphomas." (PMID 35842499, 2023). "It has been identified that Polo-like kinase 2 (PLK2) methylation-dependent transcriptional silencing occurs in B cell lymphomas, 100% of Burkitt lymphoma (BL) cell lines and a similarly high proportion of primary BL." (PMID 32010613, 2019). "As in B-cell lymphoma, abnormal methylation occurs in the CpG island of the PLK2 gene; The PLK2 expression of DG75 (EBV-) and Rael (EBV+) cell lines increase after demethylation with 5-AZA and is further upregulated by combined administration of histone deacetylase inhibitor TSA." (PMID 35898867, 2022). "In B-cell lymphoma, acute myelogenous leukemia (AML) and myelodysplastic syndromes (MDS), remarkable reduction of PLK2 expression might be related to abnormal methylation." (PMID 35898867, 2022).
Burkitt lymphoma (5 papers, 2012 to 2020). A rare form of malignant mature B-cell non-Hodgkin lymphoma. "The loss of Plk2 as a result of methylation dependent silencing of the Plk2 gene has been discovered in patients with Burkitt’s lymphoma." (PMID 22870256, 2012). "Additionally, the ectopic expression of PLK2 in Burkitt lymphoma cells increased the apoptosis rate, indicating the tumor-suppressing function of PLK2 in human cancers." (PMID 33176854, 2020). "The results indicated PLK2 play a tumor suppressive role in cervical cancer, similarly with its role in Burkitt lymphoma (BL) and epithelial ovarian cancer (EOC)." (PMID 26910911, 2016). "Remarkably, Plk2 was subject to methylation-dependent transcriptional silencing in 100% of Burkitt lymphoma (BL) cell lines and a similarly high proportion of primary BL." (PMID 22289679, 2012).
cervical carcinoma (5 papers, 2014 to 2021). A carcinoma arising from either the exocervical squamous epithelium or the endocervical glandular epithelium. "PLK2 has been reported to be tumor suppressive in B-cell neoplasia, laryngeal carcinoma, cervical cancer cell lines, and patient samples by promoting apoptosis and inhibiting cell proliferation." (PMID 35156101, 2021). "The expression of PLK2 in HPV16 (+) cervical cancer tissues was down-regulated compared to the paired para-carcinoma (P <0.01)." (PMID 26910911, 2016). "In our studies PLK2 was found to inhibit cervical cancer cell proliferation, promote paclitaxel-induced apoptosis, and reduce cell viability when exposed to paclitaxel and cisplatin." (PMID 26910911, 2016). "(iv) The up-regulation of miR-27b and down-regulation of PLK2 were confirmed in HPV16 positive cervical cancer tissues." (PMID 26910911, 2016). "MiR-27b was proved to be up-regulated by HPV16 E7 through DGCR8 to promote proliferation and suppresses apoptosis by targeting PLK2 in cervical cancer cells." (PMID 26910911, 2016). "Whether other regulating mechanism to PLK2, like CpG island methylation, exsits in cervical cancer should be studied further." (PMID 26910911, 2016). "The fact that miR-27b is up-regulated by virus oncogene E7 through DGCR8, negatively regulates PLK2 in HPV16 positive cervical cancer cells suggests that miR-27b is likely to play an oncogenic role in cervical cancer to promote cell proliferation and inhibit paclitaxel-induced cell apoptosis." (PMID 26910911, 2016). "This is the first report that PLK2 is regulated by miRNA in cervical cancer." (PMID 26910911, 2016). "This study is one step forward in understanding miR-27b-dependent regulation, provides an insight into the interaction network of viral oncogene, miR-27b and PLK2, and supports the potential strategies using miR-27b-targeted antisense nucleic acid for therapy of cervical cancer in the future." (PMID 26910911, 2016). "HPV16 E7 also promotes miR-27b expression in cervical cancer cell lines by increasing DiGeorge syndrome critical region gene 8 (DGCR8), which in turn decreases the expression of miR-27b target polo like kinase 2 (PLK2) and promotes proliferation and invasion." (PMID 30563114, 2018).
Insulin resistance (5 papers, 2020 to 2025). Increased resistance towards insulin, that is, diminished effectiveness of insulin in reducing blood glucose levels. "In addition, insulin resistance causes hyperactivity of PLK-2, pSNCA and k-resistance SNCA levels in SH-SY5Y cells of PD and PLK2 inhibitors reverse the insulin resistance-mediated abnormalities." (PMID 38441007, 2024). "Insulin resistance and T2DM lead to low Parkin and PGC1α levels, which impair mitochondrial proteins and genome expression, downregulate polo-like kinase-2(PLK2), increase ROS production, and cause abnormal mitochondrial metabolism." (PMID 39596474, 2024). "Insulin resistance increases the development and progression of PD via abnormal expression of α-synuclein, enhanced production of reactive oxygen species, mitochondrial dysfunction, and deregulation of the Polo-Like Kinase 2 Signaling." (PMID 37509049, 2023).
hepatocellular carcinoma (4 papers, 2014 to 2023). A malignant tumor that arises from hepatocytes. "We previously found that Plk2 phosphorylates Nrf2, translocating Nrf2 into the nuclei and upregulating its transcriptional activity in hepatocellular carcinoma." (PMID 35842499, 2023). "We recently found that Plk2 was highly upregulated in response to weak damage induced by doxorubicin in hepatocellular carcinoma." (PMID 35842499, 2023). "In human hepatocellular carcinoma (HCC), PLK1 acts as an oncogene and PLK2-4 presumably tumor suppressor genes." (PMID 25239093, 2014). "Also, in hepatocellular carcinoma (HCC), promotor methylation might be the reason of decreased PLK2 expression, and inhibition with siRNA could accelerate human HCC cell line growth." (PMID 35898867, 2022).
laryngeal carcinoma (4 papers, 2014 to 2021). Carcinoma that arises from the laryngeal epithelium. "We conclude that demethylated SP1 sites in CG-rich region of miR-23a-27a-24-2 cluster promoter result in the cluster overexpression, leading to proliferation promotion and apoptosis inhibition probably via targeting the related targets such as APAF-1 and PLK2 in laryngeal cancer cells." (PMID 27099864, 2016). "miR-27a acts as an oncogene in laryngeal squamous cell carcinoma through down-regulation of PLK2 and may provide a novel clue into the potential mechanism of LSCC oncogenesis or serve as a useful biomarker in diagnosis and therapy in laryngeal cancer." (PMID 25239093, 2014). "In addition, there exists the negative correlation between miR-27a and PLK2 expression levels in laryngeal cancer tissues." (PMID 25239093, 2014).
leukemia (4 papers, 2021 to 2024). A malignant (clonal) hematologic disorder, involving hematopoietic stem cells and characterized by the presence of primitive or atypical myeloid or lymphoid cells in the bone marrow and the blood. "Furthermore, we also detected elevated PLK2 protein levels in Usp18+/Δ leukemia cells compared to Usp18+/f leukemia cells." (PMID 36646704, 2023). "First, we generated doxycycline-inducible Plk2 C1498 and AE9a leukemia cells to test whether expressing Plk2 alone has any effect on leukemia development." (PMID 36646704, 2023). "Since AML levels (GFP) were restored by Plk2 inhibition and the LSC-like population was most reduced by Usp18 depletion in leukemic mice, we hypothesize that Plk2-mediated pyroptosis contributes to LSC reduction in Usp18-depleted leukemia." (PMID 36646704, 2023). "However, SgPlk2 Usp18+/Δ transplanted mice lost most of the survival benefit obtained from Usp18 inhibition, indicating that Plk2 induction contributes to leukemia cell death during Usp18 depletion in vivo." (PMID 36646704, 2023). "Importantly, we also validated the biological effect of Plk2 in WT and Usp18-depleted leukemia cells in vivo." (PMID 36646704, 2023). "Besides, some of the DMRs with the strongest increases were adjacent to genes such as CEBPA, LEF1, PLK2, MEIS1 or TLE4, which have a known involvement in either leukemia or hematopoiesis." (PMID 38972954, 2024). "Since PLK2 induced GSDME dependent pyroptosis during USP18 inhibition, we tested whether Plk2 upregulation contributes to the survival benefit of mice transplanted with Usp18 depleted leukemia cell in vivo." (PMID 36646704, 2023).
lymphoma (4 papers, 2017 to 2023). A malignant (clonal) proliferation of B- lymphocytes or T- lymphocytes which involves the lymph nodes, bone marrow and/or extranodal sites. "In TSC2+/−Eμ-Myc lymphomas, DHX9 suppression resulted in elevated levels of p21, PUMA, BAX, NOXA, BIM, c-MYC, and PLK2." (PMID 28427210, 2017).
synucleinopathies (4 papers, 2014 to 2025). "In this study, we investigated the effect of Polo-like kinase 2 (PLK2) inhibition on formation of pS129 using an ex vivo organotypic brain slice model of synucleinopathy." (PMID 34613964, 2021). "Thus, more work is needed to uncover the precise mechanisms and function of α-synuclein phosphorylation in health and disease, and accordingly whether Plk2 inhibition is a viable therapeutic target in synucleinopathies." (PMID 39372781, 2024). "PLK2 is reported to be responsible for phosphorylation of α-syn in murine brain and may potentially be responsible for the pS129-phosphorylation of the α-syn aggregates abundant in PD and other synucleinopathies." (PMID 34613964, 2021).
triple-negative breast carcinoma (4 papers, 2021 to 2025). An invasive breast carcinoma which is negative for expression of estrogen receptor (ER), progesterone receptor (PR), and human epidermal growth factor receptor 2 (HER2). "In PLK2-/- triple-negative breast cancer patient-derived xenograft (PDX) mice model, re-expression of PLK2 significantly reduces the therapeutic effect of PLK1 inhibitor Volasertib." (PMID 35898867, 2022).